TNF (tumor necrosis factor)
Diseases named in the same sentence as TNF in open-access papers (continued):
Sharing a sentence is not in itself a finding about the gene and the disease.
ileitis (59 papers, 2009 to 2026). "In TNFΔARE mice, increased TNFα expression leads to the gradual development of ileitis presenting with diarrhea and body weight loss." (PMID 31552020, 2019). "TNF-α overexpression induced ileitis as evidenced by body weight loss and increased histological inflammation in TNFΔARE mice." (PMID 26523550, 2015). "In addition, VSL#3 in the ileal epithelial cells of a type of mouse prone to develop spontaneous ileitis is associated with increased production of TNF-α and restoration of epithelial barrier function in vivo." (PMID 25978374, 2015). "Interestingly, a previous study using GF mice colonized with dysbiotic cecal microbiota of TNF∆ARE mice, which develop spontaneous ileitis due to upregulation of TNFα, demonstrated an induction of ileitis after colonization that was preceded by the loss of Paneth cell function." (PMID 37978573, 2023). "We report a 12-year-old boy with terminal ileal CD who developed severe eosinophilic gastritis and ileitis, peripheral eosinophilia, and psoriasiform dermatitis during prolonged anti-TNF treatment, despite CD remission." (PMID 42110122, 2026). "Another study reported that the administration of probiotic strains prevents the development of ileitis in vivo via stimulation of epithelial TNF-α production." (PMID 41143415, 2025). "The species Parvibacter caecicola (P. caecicola) from the phyla Actinobactera has recently been isolated from TNFΔARE mice (mouse model elevated TNF levels resulting in ileitis) and has been identified as a pathobiont for intestinal inflammation." (PMID 38068838, 2023). "GLP-2 treatment reduced levels of pro-inflammatorycytokines (IFN-γ, TNF-α, and IL-1β) and induciblenitric oxide synthase, with increased levels of IL-10 in ileitis andcolitis models." (PMID 37491005, 2023). "Quercetin, for example, has been shown to benefit in experimental murine ileitis via a reduction in NF-κB-mediated TNF-α gene expression." (PMID 37465689, 2023). "Ileitis develops spontaneously due to increased stability and production of TNF due to the deletion of the TNF AU-rich elements." (PMID 38179052, 2023). "In the TNF∆ARE model (TNFα over‐expression driven ileitis; B6/N background), the ilea showed a range of Paneth cell loss with the worst mice being similarly devoid of Paneth cells as Gpx1/2‐DKO mice." (PMID 32810389, 2020). "Ileitis even develops when TNF over-expression is restricted to intestinal enterocytes, although the disease onset and progression is delayed compared to mice with systemic TNF over-expression." (PMID 32671059, 2020). "As for the ileum, subacute ileitis induction was further accompanied by elevated systemic concentrations of pro-inflammatory cytokines such as TNF and IL-6." (PMID 30967875, 2019). "Remarkably, Psae-challenge was accompanied by even more pronounced systemic secretion of pro-inflammatory cytokines such as TNF and IL-6 at day 9 post ileitis induction." (PMID 30761129, 2019). "In a murine ileitis model increased TNF levels resulted in improved epithelial barrier functions and prevention from disease onset." (PMID 29321764, 2017). "The dose of CCX282-B was selected based on its ability to reduce ileitis severity in the TNF-ΔARE model." (PMID 26457007, 2015). "Irrespective of the genotype of mice, pro-inflammatory mediators such as nitric oxide (NO), IFN-γ and TNF-α increased multi-fold upon ileitis induction (p<0.05–0.001 vs respective naïve controls)." (PMID 25141224, 2014). "Selective overexpression of TNF in the intestinal epithelium seems to be sufficient to trigger CD-like ileitis, suggesting an important role of the epithelium in the pathogenesis of chronic intestinal inflammation in TnfΔARE/+ mice." (PMID 24849654, 2014). "Selective overexpression of TNF in the intestinal epithelium is sufficient to trigger CD-like ileitis, suggesting an important role of the epithelium in the pathogenesis of chronic intestinal inflammation in TnfΔARE/+ mice." (PMID 24849654, 2014).
ileitis (continued). "In the TNFi∆ARE/i∆ARE mouse, intestinal epithelial-specific overexpression of TNFα is sufficient to induce the development of severe ileitis." (PMID 23977323, 2013). "Based on data from mice model, CCR9 seems to induce migration of Tregs to the intestine and administration of antibodies against CCR9 in tumor necrosis factor Δadenosine uracil-rich element mice exacerbated ileitis." (PMID 23977348, 2013). "Blockade of such apoptotic pathways is central to the beneficial effects of anti-TNFα antibodies in treating Crohn’s-like murine ileitis in the SAMP1/YitFc mouse model of CD." (PMID 23977323, 2013). "Our results demonstrate a central role of TNF in ameliorating paracellular permeability during early phases of ileitis in a spontaneous model of CD-like ileitis that closely resembles the human condition." (PMID 22848704, 2012). "The goal of the present study was to determine how VSL#3 functions to promote gut health through stimulation of epithelial innate immunity, and to define the direct role of early TNF expression in preventing SAMP ileitis." (PMID 22848704, 2012). "We previously showed that the probiotic mixture, VSL#3, prevents the onset of ileitis in SAMP/YitFc (SAMP) mice, and this effect was associated with stimulation of epithelial-derived TNF." (PMID 22848704, 2012). "As expected, we found that TNF-induced ileitis correlates with enhanced IP-10 protein expression in primary ileal epithelial cells from TNFΔARE mice." (PMID 19197385, 2009). "The administration of tumor necrosis factor-α (TNF-α) inhibitors has been shown to restore the flow of intestinal substances obstructed by TLOs into the lymphatic vessels and to alleviate intestinal inflammation in ileitis mouse models." (PMID 40331987, 2025). "In response to TGF-β release, miR-511-5p level is upregulated in monocytes, resulting in their desensitization due to downregulation of TLR4 present on their surface, which controls severe inflammation and dramatically reduce TNFα and other cytokines that are involved in ileitis." (PMID 38743178, 2024). "Previous studies conducted by the authors have also demonstrated that supplementation with acrylamide results in local ileitis with such symptoms as the increased synthesis of proinflammatory cytokines by gut-associated lymphoid tissue (GALT) (Interleukin 1β (IL-1β), IL-6, TNF-α)." (PMID 32225044, 2020). "Strikingly, even higher TNF and IL-6 levels could be measured in serum samples taken from Psae as compared to mock challenged hma mice with ileitis (p < 0.01)." (PMID 30761129, 2019). "In T. gondii-induced ileitis, elicited Ly6Chi monocytes may actually prevent immunopathology by inhibiting the ability of local neutrophils to produce tissue damaging TNFα and ROI." (PMID 24942685, 2014). "In light of this new hypothesis, the development of ileitis in TNFi∆ARE/i∆ARE mice in the presence of high levels of mucosal TNFα may be explained in various ways." (PMID 23977323, 2013). "Moreover, mice that have been genetically manipulated to systemically overexpress TNFα (TNFΔARE/+ mice) develop chronic ileitis with marked similarities to Crohn’s ileitis in humans, as well as extraintestinal CD manifestations, such as inflammatory arthritis." (PMID 23977323, 2013). "Thus, B cells’ multi-faceted impact on ileitis includes generating secretory IgA, expressing LTa1b2 to drive formation of TLS, and producing LTa3 for protecting against weight loss in the presence of TNF." (PMID 38464070, 2024). "However, while TNF signaling in enterocytes causes apoptosis, it is not sufficient to cause ileitis, indicating the importance of paracrine signaling in other stromal and immune cells, rather than just enterocyte-restricted autocrine signaling." (PMID 32671059, 2020).
ileitis (continued). "Presumably, local secretion of TNFα by synoviocytes is a critical factor for the generation of proinflammatory conditions that lead to joint destruction in the TNFΔARE/+ mice; mucosal overexpression is present in both models and leads to the common phenotype of ileitis." (PMID 23977323, 2013). "Other factors that were only increased in the BALF of SHIP-1−/− mice with ileitis were IL-33 and TNFα, while IL-6, CCL2, and CCL4 were more significantly increased in the lungs of SHIP-1−/− mice with ileitis." (PMID 39432107, 2024). "This ileitis is due to the strong T-helper 1 biased immune response, characterized by the overproduction of pro-inflammatory mediators including; IFN-γ, TNFα, IL1β, IL18, and NO, commonly known as “cytokine storm”." (PMID 38743178, 2024). "Together, these data clearly indicate that intestinal TNF‐driven pathology in TNFemARE/ARE mice is dependent on the intestinal microbiota, as GF TNFemARE/ARE mice are fully protected from spontaneous ileitis development." (PMID 37694693, 2023). "Interference with the CCR9/CCL25 axis has been shown to improve disease symptoms and tissue inflammation in mouse models of ileitis such as the SAMP-1/Yit model and the TNF-ΔARE model." (PMID 26457007, 2015). "T. gondii is known to induce ileitis with CD-like immunopathology in C57BL/6 mice, i.e. CD4+ T-cell mediated inflammation dominated by Th1 cytokines TNF-α and IFN-γ." (PMID 22848538, 2012). "Treatment of resveratrol suppresses cyclooxygenase-2 activity and modulates interferon-gamma (IFN-γ), TNF-α, IL-6 and MCP-1 expression in experimental ileitis." (PMID 22069489, 2011). "Because TNF and LT are closely related cytokines, we tested whether B cell production of TNF was important for TLS organization in TNFΔARE ileitis." (PMID 38464070, 2024). "Previous studies have demonstrated that TNF‐driven intestinal inflammation in TNFΔARE mice is microbiota‐dependent, as TNFΔARE mice only develop spontaneous ileitis in colonized conditions, but not when raised under germ‐free (GF) conditions." (PMID 37694693, 2023). "In addition, TNF and NO were multi-fold elevated in MLN following ileitis induction in either cohort (p < 0.005–0.001 vs. naive)." (PMID 30761129, 2019). "Indeed, targeting the CCR9/CCL25 axis has been shown to be of benefit in the TNF-ΔARE and SAMP-1/YIT models of ileitis." (PMID 26457007, 2015). "Intestinal epithelial-derived TNFα is sufficient for the induction of Crohn’s-like ileitis, but not for the occurrence of extraintestinal manifestations, in TNFi∆ARE/i∆ARE mice." (PMID 23977323, 2013). "In the present study, we addressed the potential mechanism of action of the probiotic mixture, VSL#3, for its ability to “boost” innate mucosal immune responses by inducing TNF production, particularly during early phases of gut inflammation, in the SAMP mouse model of CD-like ileitis." (PMID 22848704, 2012). "Similarly, the genetic targeting of Phd1 in haematopoietic cells did not impact ileal inflammation in this TNF-induced ileitis mouse model." (PMID 34571764, 2021). "In addition, renal TNF and MCP-1 levels increased in hma mice upon ileitis induction (p<0.001)." (PMID 28414794, 2017). "However, except for hepatic TNF-α levels, P. aeruginosa infection did not result in more distinct pro-inflammatory cytokine secretion in liver and kidney of hma mice with ileitis." (PMID 28115993, 2017). "Notably, hepatic TNF-α concentrations were elevated in P. aeruginosa infected hma mice only (p < 0.01), but renal MCP-1 levels increased exclusively in uninfected hma mice with ileitis (p < 0.01)." (PMID 28115993, 2017). "TNF-α, nitric oxide and IFN-γ are all critical for development of necrosis in the small intestine and early mortality in C57BL/6 mice orally infected with high parasite load of ME-49 strain of T. gondii, and IL-17 is involved in ileitis in mice infected with cysts of the 76K strain by oral route." (PMID 24086456, 2013).
ileitis (continued). "Similarly, TNF-overexpressing mice (TNF∆ARE/+) used in scientific research as a model of development SpA and IBD did not develop ileitis under microbial-free conditions." (PMID 33924414, 2021).
legionellosis (59 papers, 2012 to 2025). Any disease caused by Legionella bacteria. "As use of TNF-α inhibitors increase, we urge clinicians to consider this association with legionellosis." (PMID 23092579, 2012). "Although confounding factors, such as the effect of concomitant immunosuppressive medications or disease, are possible contributors, TNF-α antagonists themselves are likely to contribute substantially to the high risk for legionellosis in these patients." (PMID 23092579, 2012). "We previously showed that TNF licenses macrophages to upregulate and rapidly activate caspase-11 in response to Legionella infection." (PMID 40530878, 2025). "It was found that the DEGs were enriched in the TNF signaling pathway, Legionellosis, MAPK signaling pathway, NF-κB signaling pathway, and chemokine signaling pathway, among others." (PMID 39335912, 2024). "In populations with compromised immune systems, such as those with chronic lung disease, or those on TNF-α inhibitors or immunomodulatory drugs, higher rates of Legionella infection have been reported." (PMID 38392911, 2024). "In this study, we demonstrate that TNF signaling licenses macrophages to die rapidly in response to Legionella infection." (PMID 37279255, 2023). "Taken together, these data indicate that TNF-α, and thus, macrophage activation, is a necessary step in the immune response against Legionella infection." (PMID 36159650, 2022). "With these findings and those of TNF-α’s role in Legionella infections, the importance of macrophage activation in the defense against infection by L. pneumophila is further reinforced." (PMID 36159650, 2022). "These included the conditions of legionellosis, the signaling pathways of TNF-regulatory, NF-kB, or NOD-like signaling." (PMID 34307149, 2021). "Severe infections included one case of intestinal tuberculosis and one case of legionellosis, both in patients treated with TNF-α-blocking agents (one in the observation group and the other in the vaccination group)." (PMID 26048579, 2015). "We therefore determined the role of TNF in DC death during Legionella infection." (PMID 40530878, 2025). "KEGG analysis revealed that the majority of target DEmRNAs were related to the TNF signaling pathway, NF-kappa B signaling pathway, IL-17 signaling pathway, legionellosis, cytokine–cytokine receptor interaction, pertussis, measles, and NOD-like receptor signaling pathway." (PMID 37504305, 2023). "Moreover, the pathways identified in KEGG were connected to legionellosis, IL-17 signaling pathway, TNF signaling pathway, and proteoglycans in cancer." (PMID 34034704, 2021). "Receipt of a tumor necrosis factor–α antagonist (TNF-α antagonists: infliximab, adalimumab, etanercept) generally has not been considered a risk factor for legionellosis." (PMID 23092579, 2012). "Given that IL-12 and TNF-α are important cytokines produced upon MyD88 signaling and critical for immunity, we then investigated whether these cytokines are required for the protection induced by an initial Legionella infection." (PMID 40558085, 2025). "Furthermore, following Legionella infection, IL-6 and TNF-α were evidently reduced in the supernatant of transfected macrophages with anti-Lpg2936 siRNA, while control-transfected macrophages showed a marked increase of both cytokines in a time-dependent manner." (PMID 32064256, 2019). "Additionally, these genes were enriched in eight KEGG pathways, including TNF signaling, estrogen signaling, pantothenate and CoA biosynthesis, neutrophil extracellular trap formation, arginine biosynthesis, glycosphingolipid biosynthesis, galactose metabolism, and legionellosis." (PMID 40760666, 2025). "Enriched Kyoto Encyclopedia of Genes and Genomes (KEGG) pathways were tumor necrosis factor (TNF) signaling, nuclear factor-kappa B (NF-κB) signaling, NOD-like receptor signaling, and legionellosis, among others." (PMID 37048115, 2023).
legionellosis (continued). "The KEGG pathway enrichment analysis of Cluster 1 showed enrichment of the TNF signaling pathway, cytokine-cytokine receptor interaction, and JAK-STAT signaling pathway, while in Cluster 2 NF-κB signaling pathway, Influenza A, and Legionellosis were enriched." (PMID 37564653, 2023). "Guidelines for preventing Legionella infection in patients receiving a TNF-α antagonist are not available; however, minimizing aerosolized exposure to untreated water sources (such as decorative fountains) is reasonable." (PMID 23092579, 2012).